NXPE3 (neurexophilin and PC-esterase domain family member 3)
Synonyms: FAM55C; MSTP115; MGC15606; MST115
Tractability: Antibody: UniProt places it where antibodies can reach, with high confidence; UniProt predicts a signal peptide or a membrane-spanning region; its Gene Ontology location is reachable by antibodies, with medium confidence. PROTAC: ubiquitination databases record sites on it.
Gene: Protein-coding gene on chromosome 3 (101,778,900 to 101,843,743, forward strand). Ensembl gene ENSG00000144815.
Subcellular location: Secreted
Subcellular location (Human Protein Atlas): Vesicles; Nucleoplasm; Predicted to be secreted
Gene Ontology:
Molecular function: protein binding
Cellular component: extracellular region
Genetic constraint (gnomAD): Loss-of-function variants: 25 observed, 43.4 expected, observed/expected ratio (o/e) 0.58, 90% interval 0.42 to 0.81. The upper end of that interval is the gene's LOEUF score, 0.81, which puts it in group 3 of 6, group 1 being the genes least tolerant of losing a copy. Missense variants: 595 observed, 688.42 expected, observed/expected ratio (o/e) 0.86, 90% interval 0.81 to 0.93. Synonymous variants: 258 observed, 263.91 expected, observed/expected ratio (o/e) 0.98, 90% interval 0.88 to 1.08.
Homologues: Orthologues: chimpanzee NXPE3 (99% identical), rabbit NXPE3 (95% identical), pig NXPE3 (95% identical), dog NXPE3 (93% identical), guinea pig NXPE3 (92% identical), mouse Nxpe3 (89% identical), rat Nxpe3 (89% identical), tropical clawed frog nxpe3 (62% identical), zebrafish nxpe3 (50% identical). Paralogues in human: NXPE2 (29% identical), NXPE4 (28% identical), NXPE1 (28% identical).
Diseases named in the same sentence as NXPE3 in open-access papers:
NXPE3 is named in the same sentence as 15 diseases in open-access papers, as found by Europe PMC text mining. Sharing a sentence is not in itself a finding about the gene and the disease. The quoted sentences say what the papers report.
COVID-19 (3 papers, 2021 to 2022). A disease caused by infection with severe acute respiratory syndrome coronavirus 2. "Gene-based analyses identified five significant gene associations with COVID-19 positivity on chromosome 3 (p < 0.05/19,148 genes = 2.6 × 10−06): NXPE3 (p = 1.6 × 10−11), ZBTB11 (p = 5.8 × 10−11), CEP97 (p = 1.0 × 10−10), RPL24I (p = 9.4 × 10−09), and PCNP (p = 6.8 × 10−07)." (PMID 35222515, 2021). "Four genes near our chromosome 3 locus—NXPE3, ZBTB11, CEP97, and RPL24I—have been linked to COVID-19 SNPs in HGI (COVID-19 Host Genetics Initiative, 2021) and studies based on HGI data." (PMID 35222515, 2021).
NXPE3 also shares sentences with these, for which no sentence is quoted: breast carcinoma (1 paper); cancer (1); clear cell renal cell carcinoma (1); colorectal cancer (1); esophageal cancer (1); hepatocellular carcinoma (1); Hypertension (1); lung carcinoma (1); non-small cell lung carcinoma (1); ovarian carcinoma (1); pancreatic cancer (1); prostate carcinoma (1); stomach cancer (1); tumor (1).